NOX4 (NADPH oxidase 4)
Diseases named in the same sentence as NOX4 in open-access papers (continued):
Sharing a sentence is not in itself a finding about the gene and the disease.
thyroid cancer (continued). "In addition, in a recent study, NOX4 expression was observed in thyroid cancer and in papillary thyroid cancer (PTC)-derived mesenchymal stem/stromal cells (MSCs), thus indicating a paracrine role for NADPH oxidase NOX4 in thyroid function." (PMID 29478325, 2019). "Further studies should determine how much the contribution rate of NOX and p22phox protein respectively to mROS and total ROS in thyroid cancer cells exactively are, and how the sensitivity of cell response to thyroid related hormones is when NOX4 and p22phox protein levels are altered by someway." (PMID 30367082, 2018). "Therefore, in order to study the NOX4 activator, p22phox as with NOX4, can assist in the level of mROS in thyroid cancer cells upon hypoxia, p22phox knockout in TPC-1 cells was prepared mediated by CRISPR/Cas9 system." (PMID 30367082, 2018). "Moreover, it was demonstrated that NOX4 are overexpressed in thyroid cancers, linking this H2O2-generating system to cancer pathogenesis." (PMID 30558263, 2018). "The findings suggest that NOX4 has the function of regulating the basic state of mitochondria, which may be one of the reasons why the proliferation of thyroid cancer cells slows down." (PMID 30367082, 2018). "It was found that NOX4 is directly involved in this process, and its inhibition restored NIS expression in thyroid cancer cells." (PMID 38089632, 2023). "Recent study showed that GLX351322, a NADPH oxidase 4 (NOX4)-derived ROS inhibitor, has an inhibitory effect on thyroid carcinoma cell growth and disrupts the resistance of cancer cells to etoposide." (PMID 36770846, 2023). "NOX4 is a critical mediator of cell dedifferentiation and NIS repression in thyroid cancers harboring BRAFV600E oncoprotein." (PMID 35682803, 2022). "NOX1, NOX3, and NOX5 expression suggested minor changes in thyroid cancers, whereas the expression of NOX2 and NOX4 showed increased mRNA synthesis in papillary thyroid and anaplastic thyroid cancers." (PMID 26664298, 2015). "As a conclusion, according to our data PC Cl3, PC PTC1, PC E1A cell model systems corresponded to human NOX2, NOX4, SOD3, CATALASE, GPX5, and GPX7 gene expressions in thyroid cancer." (PMID 26664298, 2015). "Furthermore, in contrast to other DUOX enzymes, the expression of NOX4 is regulated by TSH and up‐regulated in thyroid cancer." (PMID 40620232, 2025). "We previously showed a positive correlation between NOX4 mRNA and BRAFV600E mutation in about 500 PTC from TCGA data, but this has not been established at the protein level in thyroid cancer tissues." (PMID 37504283, 2023). "ERKs or PI3K/AKT signals in thyroid cancer are critical, we hypothesized that ERKs or PI3K/AKT as downstream survival signals are activated by NOX4." (PMID 35396551, 2022). "In thyroid cancer models, NOX4 expression has been detected in papillary thyroid tumors and was shown to be stimulated by RAS and adenovirus E1A oncogenes, suggesting that NADPH oxidase NOX4 is a mediator of oncogene action." (PMID 29478325, 2019). "Strikingly, we found that HIF1α rescued the decreased proliferation of NOX4 knockdown cells, but not restoring the mROS levels, reflecting that NOX4 regulates thyroid cancer cell growth dependent on mROS-HIF axis, rather than HIF-mROS." (PMID 30367082, 2018). "Interestingly, goiter and hyperplasia tissues with a high score of NOX4 protein also showed nuclear and perinuclear localization, questioning the potential role of NOX4 in the progression of these non-malignant diseases to thyroid cancer." (PMID 37504283, 2023). "Gene expression of NOX4, DUOX1 and DUOX2 was not increased in kidney and thyroid cancers with high-level apoptosis and energy metabolism (data not shown), implying some other genes acting as the indicators of oxidative stress." (PMID 28582771, 2017). "Interestingly, Src activation by NOX4-derived H2O2 has already been demonstrated in cancer and non-cancer contexts, suggesting a possible interplay between NOX4 and PBF signaling in thyroid cancer." (PMID 35682803, 2022).
thyroid cancer (continued). "Thus, the Oncomine Giordano and He database results showing thyroid cancer-related redox gene expression suggest that NOX1, NOX3, and NOX5 mRNA levels do not markedly change in tumorigenesis, whereas NOX2 and NOX4 expression showed increased levels correlating with the degree of transformation." (PMID 29478325, 2019).
colorectal cancer (25 papers, 2015 to 2025). A primary or metastatic malignant neoplasm that affects the colon or rectum. "NOX4 overexpression in human colorectal cancer was associated with poor prognosis and increased tumor migration and invasion." (PMID 32414400, 2020). "However, the role of NOX4 in colorectal carcinoma and the underlying molecular mechanism responsible for its involvement in tumorigenesis and/or tumor progression are far from clear." (PMID 28422720, 2017). "In this research, we suggested that CBD mediates anti-inflammatory and anti–cancer activity via NOX4-mediated ER stress response and apoptotic cell death in colorectal cancer cells." (PMID 41465451, 2025). "A study found that the increased ROS induced by NOX4 is essential for oleic acid promoting the metastasis of colorectal cancer cells." (PMID 41311830, 2025). "In SW480 colorectal cancer cells, OA promoted cell migration and invasion by the induction of NADPH oxidase 4 (NOX4), accompanied with increased levels of ROS and MMP-1/9." (PMID 37373069, 2023). "Up-regulation of NOX4 predicted worse prognosis and accelerated tumor growth in colorectal carcinoma." (PMID 36915111, 2023). "There is a recent report showing that tissue-specific deletion of Nox4 gene promoted tumor formation in carcinogen-induced colorectal cancers and fibrosarcomas." (PMID 35836253, 2022). "NOX4 is presented in the literature as a therapeutic target in digestive cancer, including in colorectal cancer, being correlated among others with VEGF, MAPK and PI3K/AKT." (PMID 34073426, 2021). "In another study, the Oncomine database was utilized to retrieve six different studies showing NOX4 is highly expressed in colorectal carcinoma." (PMID 33557266, 2021). "A recent study demonstrated that overexpression of NOX4 can promote tumor progression and predict poor prognosis in human colorectal cancer." (PMID 32457797, 2020). "Recent study found that NOX4, as a CS-related gene in colorectal cancer, may be a key factor in driving colorectal cancer resistance by altering TME." (PMID 39355236, 2024). "Indeed, silver NPs (AgNPs) also induced apoptosis in colorectal cancer cells by upregulating the expression of NOX4." (PMID 36838869, 2023). "Our findings suggest that Nox4 is involved in CBD-mediated intracellular ROS release and plays a role in regulating CBD-induced apoptosis in colorectal cancer cells." (PMID 41465451, 2025). "There is evidence that the upregulation of NOX4, CXCL8, CXCL5, GDF15, and MMP13 genes in colorectal cancer promotes the metastasis of cancer cells, so a sustained upregulation of these genes after aspirin treatment will not benefit from treatment." (PMID 41425852, 2025). "In CBD-treated colorectal cancer cells, cell viability was maintained, and the levels of intracellular ROS, cytotoxicity LDH, and caspase-3 activity were suppressed when NOX4 was knocked down or when DPI or NAC was administered." (PMID 41465451, 2025). "CBD promotes apoptosis in colorectal cancer cell lines through a mechanism involving the PERK-CHOP signaling pathway, intracellular Ca2+ and ROS production, and the upregulation of NOX4." (PMID 41465451, 2025). "However, the regulation and function of NOX4 in colorectal carcinoma and its relationship with clinicopathological features including prognosis of CRC patients remains to be elucidated." (PMID 28422720, 2017). "NOX4 acts as a powerful modulator of CBD-induced ROS production, and its subsequent activation induces ER stress-induced apoptosis via intracellular ROS and Ca2+ release in CBD-treated colorectal cancer cell lines." (PMID 41465451, 2025).
colorectal cancer (continued). "A similar targeting profile was observed for hsa-miR-192-5p: the canonical form bound EMT master-regulator ZEB2 and angiogenesis stimulator WNK1, while non-canonical 5′-isomiR regulated two other colorectal cancer oncogenes: NOX4 and MSN." (PMID 36275459, 2022). "NOX4, as a member of the NADPH oxidase family, is widely expressed in various tumor cells and has been reported to be activated to promote tumor metastasis in some tumors such as human colorectal cancer and non-small cell lung cancer." (PMID 33499904, 2021). "NADPH oxidase 4 (NOX4), a major source of reactive oxygen species (ROS) production, has been increasingly reported to be involved in tumorigenesis and/or tumor progression, but limited data are available regarding the role of NOX4 in colorectal carcinoma (CRC)." (PMID 28422720, 2017). "Through inhibitory experiments, it was observed that NOX4 knockdown and DPI orNAC treatment block various cellular responses, including specifically intracellular ROS release, caspase-3 activity, LDH cytotoxicity, and the PERK-CHOP cascade, in colorectal cancer cells." (PMID 41465451, 2025).
hepatocellular carcinoma (24 papers, 2013 to 2025). A malignant tumor that arises from hepatocytes. "As an example, gene deletions in NOX4 have been documented in association with the hepatocellular carcinoma of a high tumor grade, and NOX4 knockdown studies showed an elevated proliferative capacity of liver tumor cells in vitro." (PMID 30935064, 2019). "In the present work, we examined the role of NADPH oxidase 4 (Nox4) in LPS-induced TLR4 responses in human hepatoma cells and wildtype and Nox4-deficient mice." (PMID 29085012, 2017). "Indeed, studies that evaluated the total cellular levels of NOX4 found that NOX4 was associated with favorable prognostics in hepatocellular cancers (HCC)." (PMID 35269843, 2022). "The goal of this study, therefore, is to evaluate the role of Nox4 in the LPS induced responses in a well-characterized human hepatoma cell line, primary hepatocytes isolated from control wildtype (Nox4+/+) and Nox4-deficient (Nox4−/−) mice, and in these animals in vivo." (PMID 29085012, 2017). "Epicatechin even promotes lower lipid deposition and NOX3/NOX4 expression in a human hepatocellular cancer cell line incubated with palmitate." (PMID 39980683, 2025). "The expression of L-HDAg in hepatoma cells has also been shown to promote superoxide anion production accompanied by the induction of NADPH oxidase 4 (NOX4) and activation of NF-κB signaling." (PMID 37107349, 2023). "Nox4 is highly upregulated in tumor compared to healthy liver tissue of mice that spontaneously develop liver tumors, and in humans, Nox4 is upregulated in hepatocellular carcinoma and other cancers." (PMID 32680543, 2020). "In summary, the present study provides evidence that Nox4 mediates LPS-TLR4 signaling in human hepatoma cells and murine hepatocytes in vitro through the TLR4-Nox4-NF-κB and TLR4-Nox4-AP-1 signaling pathways." (PMID 29085012, 2017). "These include Trim24, a female-biased transcriptional regulator and tumor suppressor for hepatocellular carcinoma that is induced by cGH within 10 h, and Nox4, a cGH-repressed male-biased gene involved in liver oxidative stress and stellate cell activation." (PMID 28694329, 2017). "The results of previous studies together with the present data indicate that Nox4 mediates the LPS-TLR4 signaling in human hepatoma cells." (PMID 29085012, 2017). "We present evidence that Nox4 mediates LPS-induced TLR4 signaling in human hepatoma cells and murine hepatocytes as well as liver and plasma in whole mice in vivo." (PMID 29085012, 2017). "Furthermore, some studies have reported the prognostic value of NOX4 in cancer, including colorectal, gastric, and endometrial cancer, hepatocellular carcinoma, esophageal and tongue squamous cell carcinoma, and retinoblastoma." (PMID 35265227, 2022). "Elevated levels of NOX4 protein and mRNA have been identified in cancers of various origins; an example of this is its increased expression in premalignant fibrotic states that can lead to lung and liver carcinomas." (PMID 36290761, 2022). "Thus, we suggest that further studies should be conducted on the impact of NOX4 expression in hepatocellular carcinoma." (PMID 35265227, 2022). "Moreover, the prognostic value of NOX4 expression has been reported as numerous cancers, such as colorectal, gastric, and endometrial cancer, hepatocellular carcinoma, esophageal and tongue squamous cell carcinoma, and retinoblastoma." (PMID 35265227, 2022). "Investigations of other tumor’s entities indicated that NOX4-derived ROS may limit tumor progression (liver carcinoma) and that TRPM2 overexpression may enhance induction of cell death by H2O2 (neuroblastoma)." (PMID 31671815, 2019). "Nox4 downregulation also attenuates the proliferation of Huh7 hepatoma cells upon LPS stimulation." (PMID 29085012, 2017). "Therefore, our data suggest that Nox4 mediates LPS-TLR4 signaling in human hepatoma cells and murine hepatocytes and may contribute to the ability of LPS to stimulate liver pathology." (PMID 29085012, 2017).
hepatocellular carcinoma (continued). "FGF21 promotes ferroptosis in hepatocellular carcinoma by upregulating Major vault protein (MVP), which enhances NOX4-mediated ROS production through IRF1 and YAP1 interactions." (PMID 39315094, 2024). "Evidence from patient-derived GBM stem cell experiments suggests that TGFβ upregulates the expression of NADPH oxidase 4 (NOX4) protein, which also occurs in other cancer cell types like hepatocellular carcinoma." (PMID 36169772, 2022). "With regard to the cancer type, the results indicated an association between high NOX4 expression and poor DFS in the subgroup of all other cancers (HR: 1.87, 95% CI: 1.30–2.68, p < 0.001), but not with hepatocellular carcinoma." (PMID 35265227, 2022). "In this work, we observed that TGFβ upregulated NOX4 expression in patient‐derived GSC, a regulatory event that takes place in other non‐tumoural and in cancer cell types such as hepatocellular carcinoma, with the immediate consequence of increasing the intracellular ROS levels." (PMID 35203105, 2022).
fibrosis (22 papers, 2012 to 2026). the formation of excess fibrous connective tissue in an organ or tissue in a reparative or reactive process. "In IPF patients, upregulated Nox4 expression was found in thickened pulmonary arteries, suggesting a potential role for Nox4 in fibrosis-associated vascular remodeling." (PMID 32360174, 2020). "Nox1 or Nox4-deficient mice show inhibited the development of CCl4-induced fibrosis, and Nox4 was also reported to be necessary for TGFβ-induced HSC activation and hepatocyte death." (PMID 31861818, 2019). "NOX4 was increased in the alveolar epithelium of IPF lungs, and global deletion of NOX4 protected mice from bleomycin-induced fibrosis." (PMID 36139863, 2022). "In conclusion, Nox4-generated H2O2 is beneficial for the host in decreasing pathogen colonization but has only minimal impact on collagen deposition in this fibrosis model." (PMID 33059312, 2020). "Nox4 is upregulated in animals with CCl4-triggered fibrosis as well as in the liver of HCV-infected patients with virus-associated fibrosis." (PMID 31861818, 2019). "In the lung, it has been shown that some pro-oxidant enzymes such as NADPH oxidase-1 (NOX1), NOX2, NOX4, as well as Duox1 and Duox2 are involved in oxidative stress and development of fibrosis." (PMID 31366142, 2019). "Finally, NOX4 expression was elevated in patients with hepatitis C virus (HCV)-derived fibrosis, increasing along the fibrosis degree." (PMID 23049784, 2012). "Importantly, AT1-induced cardiac fibrosis and remodeling might be caused by ROS production via AT1/NOX4 interaction." (PMID 37968296, 2023). "Therefore, it is likely that NOX4 plays an important role in the pathogenesis of SSc fibrosis." (PMID 34682914, 2021). "In this modified fibrosis model stable AIEC colonization was achieved at all time points, resulting in higher AIEC burden in Nox4−/− mice." (PMID 33059312, 2020). "The DSS/AIEC fibrosis model did not lead to a significant rise in insoluble collagen in either mouse strain, and fibrosis-associated Tgfb, Col1a, Loxl2 and Nox4 genes were either only slightly increased or not altered, and only minimally downregulated in Nox4−/− mice." (PMID 33059312, 2020). "Genetic and pharmacological inhibition of NOX4 (with NOX4 siRNA and GKT137831) in older mice with established fibrosis attenuated the senescent and apoptosis-resistant myofibroblast phenotype and led to a reversal of persistent fibrosis." (PMID 26370974, 2015).